INS (insulin)
Diseases named in the same sentence as INS in open-access papers (continued):
Sharing a sentence is not in itself a finding about the gene and the disease.
tumor (continued). "Insulin and IGFI stimulate the proliferation of tumour cells in vitro and promote glucose uptake in the subset of tumours that are insulin-dependent." (PMID 25961014, 2015). "We observed reduced blood glucose and serum insulin levels along with decreased proliferating cell nuclear antigen (PCNA) and bromodeoxyuridine positive (BrdU+) tumor cells in 2-DG fed mice." (PMID 26135741, 2015). "Taken together, our data suggest that neoplasia formation correlates with gut regions having higher rates of ISC proliferation and is affected by modulation of Insulin and Jnk signaling pathways, correlating with stem cell proliferation rates." (PMID 26607382, 2015). "TRB3 depletion protects against tumour-promoting actions of insulin/IGF and attenuates tumour initiation, growth and metastasis in mice." (PMID 26268733, 2015). "Therefore it could be that various insulin analogues have different tumour promoting properties." (PMID 26242987, 2015). "The phosphorylation of PKB/Akt (Ser473) was assessed in tumor tissue as a marker of PI3K pathway activation and potential insulin-dependent effects of metformin." (PMID 25849721, 2015). "Decreased tumor expression of the IR, combined with reduction in PI3K and Ras-MAPK signaling following metformin administration, points to the indirect insulin-dependent effects of metformin as its mechanism of antitumor action in the neoadjuvant setting." (PMID 25849721, 2015). "Numerous pharmaceutical agents designed to specifically target the insulin/IGF system have been developed and tested for their tumor-inhibiting effects." (PMID 26029167, 2015). "The activation of insulin/IGF receptors triggers signalling cascades of the PI3K-AKT and MAPK/ERK pathways that promote mitogenesis and antagonize apoptosis in tumour development." (PMID 26268733, 2015). "In conclusion, these effects of dietary 2-DG on blood glucose, insulin, PI3K/Akt signaling, proliferation, immune status and MMP-9 activity provide a plausible mechanism for the tumor inhibitory effects of such metabolic intervention." (PMID 26135741, 2015). "An interesting observation is that metformin was the most efficient in reducing insulin and IGF-1 levels in the HED group, consistent with the highest tumor reduction by metformin observed in the HED group." (PMID 25895126, 2015). "In view of the lifelong exposure and large patient populations involved, insulin analogs with increased mitogenic effects in comparison to human insulin may constitute a major health problem, since these analogs could induce the growth of pre-existing neoplasms." (PMID 24904529, 2014). "Insulin down-regulates expression of insulin-like growth factor-binding proteins within the breast, increasing the bioavailability of IGF-1 and stimulating tumour development." (PMID 25338520, 2014). "The ectopic origin of the tumour is demonstrated by functional imaging (68Ga-Dotanoc and 99mTc-HYNICTOC), and by immunohistochemistry for insulin staining." (PMID 24741994, 2014). "Excess body weight is related to higher level of insulin and insulin-like growth factor I (IGF-1) which promote certain types of tumor cell proliferation and growth." (PMID 25198347, 2014). "In view of the lifelong exposure and large patient populations involved, insulin analogs with an increased mitogenic effect in comparison to human insulin may potentially constitute a major health problem, since these analogs may possibly induce the growth of pre-existing neoplasms." (PMID 24904529, 2014). "The altered phosphorylation of Akt and mTOR in HED and CRD tumors correlated with the corresponding levels of insulin and IGF-1 and the tumor growth observed in the respective groups." (PMID 25026276, 2014). "Growing experimental and clinical evidences demonstrated that insulin and IGF-1 receptor family are commonly expressed and have important roles in various neoplasia, rendering them as promising therapeutic targets." (PMID 24970814, 2014).
tumor (continued). "High levels of insulin and IGF-I have important role in the alterations of cell proliferation and in tumor induction, particularly in breast and prostate." (PMID 23061769, 2013). "We used these supra-pharmacological doses of insulin, X10 and IGF-1 because the increased tumor incidence in previous studies was observed after treatment with supra-pharmacological doses of X10." (PMID 24260289, 2013). "The relative increased expression of INSR (a receptor for insulin) and IGF1 in the resistant cohort in our study indicates that the drug resistant cells evolve multiple compensatory mechanisms for tumour cell survival." (PMID 24237932, 2013). "Insulin levels in HFD-E and LFD tumor-bearing mice varied widely and generally were in the hyperinsulinemic range." (PMID 24156623, 2013). "We evaluated the effect of insulin and IGF-I stimulation in the expression profile of EMT markers as well as in tumor cell invasion." (PMID 24282611, 2013). "These expression data along with probing of insulin signaling in cell culture, suggest that MT19c is down-regulating these pro-growth and survival pathways in SKOV-3 as part of its anti-tumor activity." (PMID 21781307, 2011). "After digestion of tumor biopsies with collagenase and trypsin, cell suspensions were cultured in Mammary Epithelial Basal Medium supplemented with EGF, insulin, hydrocortisone, bovine pituitary extract (MEGM) and 1–2% FBS for up to 5 days." (PMID 21264259, 2011). "Second, high insulin and insulin-like growth factor (IGF)-1 levels resulting from chronic ingestion of CHO-rich Western diet meals, can directly promote tumor cell proliferation via the insulin/IGF1 signaling pathway." (PMID 22029671, 2011). "Angiogenesis, the formation of new blood vessels, has a vital function in tumour growth and spread, and IGF-1 and insulin induce angiogenesis in vitro and in vivo." (PMID 21081932, 2011). "In summary, all these studies indicate that insulin, IGF-1, IGF-2, and their signalingvia the IR and IGF-1R can induce tumor growth." (PMID 23908801, 2011). "Circulating levels of IGF-I and IGFBP-3 are relatively high, however (about 500–1000 times the concentration of insulin, for example), and it is very unlikely that increased synthesis of IGF-I or IGFBP-3 by tumours would substantially alter circulating levels." (PMID 14583772, 2003). "Another theoretical source of bias would be influences of a tumour on circulating levels of IGF-I, IGFBPs, or insulin." (PMID 14583772, 2003). "Similarly, reducing dietary intake specifically of the amino acid methionine reduces insulin, IGF-1, oxidative stress, and inflammation, and reduces tumor growth in animal models." (PMID 40285503, 2025). "Tumor fragments were cultured in ultra-low attachment plates containing a specific GBO medium composed of 50% of DMEM F12 and NeurobasalTM medium supplemented with NEAAs, N2, B27, human insulin, and 2-mercaptoethanol." (PMID 41226697, 2025). "Single cell transcriptomic analysis of human pancreatic neuroendocrine tumours has previously been reported, but no studies to date have included functional insulin-producing tumours." (PMID 40438247, 2025). "These cells were insulin-negative, suggesting tumor cell invasion into the islet rather than conversion of targeted cell to endocrine cell." (PMID 39548190, 2025). "Laboratory tests showed that blood glucose, insulin and gastrin levels were normal, and the pNET was considered non-functional; however, the tumor was resected due to its large size." (PMID 40421248, 2025). "The diagnosis is confirmed by detecting high levels of anti-insulin antibodies without any alteration of the pancreas, lack of previous exposure to exogenous insulin, and absence of neoplasia." (PMID 40584814, 2025). "Additionally, IGF‐1 and insulin can upregulate the expression of vascular endothelial growth factor (VEGF), increasing tumor angiogenesis and further promoting tumor growth." (PMID 40550558, 2025).
tumor (continued). "We extend these findings using the LLC tumour model by reporting that glucose, but not insulin, was increased in the LLC compared with PBS despite similar food consumption." (PMID 40931444, 2025). "For instance, elevated insulin levels can stimulate cell proliferation via the insulin-like growth factor-1 (IGF-1) axis while inducing epithelial-mesenchymal transition (EMT), thereby enhancing tumor invasiveness." (PMID 41164182, 2025). "We focused on whether circulating LEAP2 levels are altered in patients, how they relate to insulin and ghrelin, and whether LEAP2 is expressed in tumor tissues." (PMID 41488138, 2025). "The impact of systemic metabolism and diet on tumour evolution is still not fully comprehended, necessitating new experiments exploring the influence of systemic metabolic controllers such as insulin and glucagon." (PMID 40649254, 2025). "Sulfonylureas, as insulin secretagogues, may elevate IGF and insulin levels, promoting tumor development." (PMID 39333445, 2024). "These dietary interventions help restore mitochondrial size, muscle integrity, and insulin signalling; enhance mitochondrial membrane potential; and improve cellular energy production, although they do not affect tumour size." (PMID 39682725, 2024). "The increase in insulin levels can act as a direct growth-promoting signal and the elevated free bioactive insulin-like growth factor 1 (IGF1) can indirectly alter the cellular environment favorably for tumor development." (PMID 38255203, 2024). "Interestingly, in rare instances in which the pancreatic tissue section included both the PDAC tumor and the adjacent islets, high sorcin levels in PDAC tumors coincided with low insulin levels and PDX1 levels in tumor-adjacent islets." (PMID 39516378, 2024). "In addition, we found that the insulin/lncRNA DGUOK‐AS1/microRNA‐145‐5p (miR‐145‐5p) axis controls SIX1 expression, DNL, and tumor growth and metastasis." (PMID 39258807, 2024). "In vivo, the pharmacological inhibition of RAGE halted insulin-induced tumor growth, without affecting blood glucose homeostasis and RAGE-induced insulin resistance, a condition associated with aberrant IGF activation." (PMID 38892104, 2024). "Using a Drosophila tumor model originating from nonreproductive tissue, we show that female-biased tumor growth involves multifaceted communications among tumor cells, hemocytes, and neuroendocrine insulin-producing cells (IPCs)." (PMID 39642218, 2024). "Moreover, tumor-bearing mice in which DNMT1 was targeted exhibited a notable stability in both blood glucose and serum insulin levels." (PMID 38755637, 2024). "The tumor cells recruit circulating hemocytes to the TME, triggering JNK activation, which subsequently induces cytokine Unpaired 2 (Upd2)/leptin expression that promotes secretion of Dilp2 from insulin-producing cells (IPCs)." (PMID 39642218, 2024). "Here we show that the insulin-INSR axis drives OC cell proliferation and influences response to platinum, supporting the idea that overexpression of INSR could drive tumor progression." (PMID 39622796, 2024). "Lacking of exon 11 encoding 12 amino acids located at the carboxy‐terminal domain of extracellular subunits, INSR‐A has high affinity to insulin and IGFs and contributes to fetal development and tumor progression, while INSR‐B only binds to insulin and regulates glucose and lipid metabolism." (PMID 38952575, 2024). "Versus mice fed an isocaloric Western diet (44% kcal of carbohydrates), mice fed a no-carbohydrate diet had prolonged survival, smaller tumors, reduced insulin, and increased insulin-like growth factor-binding protein 3 (IGFBP3), which has tumor suppressing activity." (PMID 38082056, 2024).
tumor (continued). "In vivo, the pharmacological inhibition of RAGE halted Insulin-induced tumor growth, without affecting blood glucose homeostasis." (PMID 37461077, 2023). "We show that the insulin and TGF‐β signalling pathways are deregulated in the peripheral tissues in tumour bearing animals, their disruption can recapitulate some aspects of tissue wasting, and their modulation can rescue tissue wasting in the presence of a tumour." (PMID 38014610, 2023). "Several matrix metalloproteinases (MMPs) were up-regulated in tumour samples, namely MMP12 (5.1-fold), MMP14 (2.3-fold) and MMP2 (2.2-fold), which cleave elastin (and insulin), collagen (and other extracellular proteins, such as aggrecan) and certain collagens (and gelatin), respectively." (PMID 37397358, 2023). "Therapeutic strategies that target insulin/AMPK signaling and/or multi-TKI inhibitors that target ROS, ALK, KIT, FAK, TIE2, SRC, etc., may specifically target the tumor biology of these poorest-prognosis patients." (PMID 38086377, 2023). "Activation of insulin signalling, inhibition of TGF‐β signalling, or modulation of ECM levels via SPARC, Rab10 or Collagen IV in the fat body, is able to rescue tissue wasting in the presence of tumour." (PMID 38014610, 2023). "The pancreas can release compensatory insulin (insulin feedback) to restore the body to normal glucose homeostasis, however this insulin feedback may reactivate PI3K/AKT/mTOR signalling in tumours, thereby affecting the effect of targeted therapy." (PMID 37489050, 2023). "Insulin can also stimulate the production of IGF-1, which promotes tumor growth." (PMID 37215444, 2023). "The difference in insulin staining between the tumours expressing GLP-1R and those lacking GLP-1R expression was statistically significant (p < 0.002)." (PMID 37894845, 2023). "Further evidence of Neu-1′s involvement in IR signaling is that in-vitro and in-vivo studies have concluded that insulin affects tumor progression by acting on the IR and not solely by IGF-1R cross-talk." (PMID 36831374, 2023). "The impact of alpelisib and STX-478 doses on insulin sensitivity was analyzed using an insulin tolerance test (ITT) and oral glucose tolerance test (OGTT) following 5 days of repeat dosing in non–tumor-bearing, female BALB/c nude mice, the sex/strain frequently used in our xenograft studies." (PMID 37623743, 2023). "Similar to LDL cholesterol add-back, administering recombinant insulin, IGF1 and leptin to Capan-1 xenograft-bearing mice abolished fasting-induced enhancement of terbinafine activity and it also restored cholesterol content in the tumours." (PMID 37907500, 2023). "Insulin administration did not significantly increase 18F-FDG uptake ratios of tumor to reference tissues in diabetic mice." (PMID 37884546, 2023). "The genetic changes affecting insulin metabolism, immune responses and DNA repair are biologically advantageous, but elevation of Ki67 in tumour tissue is not." (PMID 37334023, 2023). "In this vein, we performed a TaqMan Gene Expression Assay consisting of a Human Tumor Metastasis Array in BCAHC-1 cells exposed to insulin in the presence or absence of metformin." (PMID 35672854, 2022). "Other studies have shown that the effects of calorie restriction can in some tumors influence tumor growth by altering lipid metabolism independent of insulin signaling." (PMID 36062923, 2022). "Insulin is regarded as strong growth factor and mitogen which is able to stimulate cell proliferation and inhibit apoptosis and increase bioactivity of IGF-1 to exert tumor-promoting effects." (PMID 35296101, 2022). "Finally, the signaling crosstalk between insulin and insulin-like growth factor-1 receptor (IGF-1R) is closely related to tumor development." (PMID 35933633, 2022). "(a) Changes in metabolites in T2D patients, such as in insulin/IGF-1 and leptin/adiponectin secretion, may favor tumor development." (PMID 36553697, 2022).
tumor (continued). "We also monitored the blood glucose of mice treated with acarbose and insulin and find that the effect of acarbose and insulin on anti-PD1 tumor inhibition was not related to blood glucose." (PMID 36033393, 2022). "Our protein library contained 17 proteins in the context of an infection (CMV, HPV, EBV, HBV, mumps, LPS), tumor and cellular stress response (HSP27, HMGB1, CRT, HO-1, HO-2, IL8), autoimmunity (insulin, collagen, vimentin, albumin) or others (ovalbumin, bovine serum albumin)." (PMID 36429087, 2022). "Further, they reduce the insulin and IGF-1 secretions, which are involved in tumor growth." (PMID 36139562, 2022). "Moreover, insulin is also capable of downregulating AMPK pathway and upregulating mTOR pathway to inhibit metabolism and mitosis of tumor cells and selectively killing tumor stem cell." (PMID 35296101, 2022). "A high insulin microenvironment can upregulate the expression of G-protein-coupled estrogen receptor (GPER) in EC cells, increasing the sensitivity of tumor cells to estrogen and facilitating tumor cell proliferation." (PMID 36551694, 2022). "Scribble has previously been reported to play varied roles as a tumor suppressor but its possible role in glucose uptake in insulin signaling has not been reported." (PMID 36376971, 2022). "While we cannot completely rule out a direct effect of dapagliflozin to reduce tumor glucose uptake independently of insulin, two data sets argue against this interpretation." (PMID 35595952, 2022). "However, PNETs are known to be a particularly metabolically active tumor type, and our analysis indicated that MK2 affects macrophage-dependent production of metabolic factors such as insulin, leptin and resistin in PNETs." (PMID 36362348, 2022). "Pancreatic or pharmaceutical insulins are unlikely to influence tumour progression if tumours synthesise insulin in biologically significant amounts." (PMID 34554347, 2022). "If the SGLT2 inhibitor were acting directly to reduce tumor glucose uptake, insulin infusion would not be expected to fully abrogate the effect of dapagliflozin." (PMID 35595952, 2022). "Tumor growth correlated with serum glucose (p < 0.01), leptin (p < 0.01), and ghrelin levels (p < 0.01), but not with serum insulin levels." (PMID 35361802, 2022). "We found that the relatively modest positive correlations between fasting insulin levels and PanIN plus tumor area were significant in female mice, but not in males." (PMID 35189981, 2022). "Metformin mitigated tumor growth in HFD-fed mice, paralleled by reductions in circulating glucose, insulin, soluble P-selectin, TGF-β1 and High Mobility Group Box-1 (HMGB1), as well as tumor expression of cell proliferation, aerobic glycolysis, glutaminolysis, platelets and neutrophils molecules." (PMID 36012397, 2022). "In both mouse models, systemic Akt2 deletion elevated insulin levels and either did not affect tumor progression or exacerbated tumor growth and metastasis." (PMID 35578699, 2021). "This opens the possibility that the production of insulin and the hybrid polypeptide translated from INS-IGF2 transcript in the tumours may contribute both to autocrine tumour growth effects and the glucose imbalances seen in these patients." (PMID 34170845, 2021). "Previous investigations have shown that tumor rates are higher in diabetic patients treated with insulin-releasing drugs, but not in patients treated with metformin, which did not increase insulin levels." (PMID 33727597, 2021). "Interestingly, the proteoglycan decorin acts as a tumor suppressor by binding and negatively regulating IGF1, IGF2, insulin, IGF1R and IR-A activity." (PMID 34440844, 2021). "In vitro experiments proved that insulin induces EMT, invasion and migration of tumor cells." (PMID 33842335, 2021).